TRBV6-7 (T cell receptor beta variable 6-7 (non-functional))
Description:
Probable non-functional open reading frame (ORF) of V region of the variable domain of T cell receptor (TR) beta chain. Non-functional ORF generally cannot participate in the synthesis of a productive T cell receptor (TR) chain due to altered V-(D)-J or switch recombination and/or splicing site (at mRNA level) and/or conserved amino acid change (protein level). Alpha-beta T cell receptors are antigen specific receptors which are essential to the immune response and are present on the cell surface of T lymphocytes. Recognize peptide-major histocompatibility (MH) (pMH) complexes that are displayed by antigen presenting cells (APC), a prerequisite for efficient T cell adaptive immunity against pathogens. Binding of alpha-beta TR to pMH complex initiates TR-CD3 clustering on the cell surface and intracellular activation of LCK that phosphorylates the ITAM motifs of CD3G, CD3D, CD3E and CD247 enabling the recruitment of ZAP70. In turn ZAP70 phosphorylates LAT, which recruits numerous signaling molecules to form the LAT signalosome. The LAT signalosome propagates signal branching to three major signaling pathways, the calcium, the mitogen-activated protein kinase (MAPK) kinase and the nuclear factor NF-kappa-B (NF-kB) pathways, leading to the mobilization of transcription factors that are critical for gene expression and essential for T cell growth and differentiation. The T cell repertoire is generated in the thymus, by V-(D)-J rearrangement. This repertoire is then shaped by intrathymic selection events to generate a peripheral T cell pool of self-MH restricted, non-autoaggressive T cells. Post-thymic interaction of alpha-beta TR with the pMH complexes shapes TR structural and functional avidity.
Synonyms: TRBV67; TCRBV13S8P; TCRBV6S7
Gene: T-cell receptor variable (V) gene on chromosome 7 (142,487,863 to 142,488,295, forward strand). Ensembl gene ENSG00000253188.
Subcellular location: Cell membrane
Gene Ontology:
Biological process: cell surface receptor signaling pathway
Cellular component: plasma membrane
Homologues: Paralogues in human: TRBV6-8 (86% identical), TRBV6-5 (85% identical), TRBV6-2 (83% identical), TRBV6-6 (83% identical), TRBV6-1 (82% identical), TRBV6-4 (69% identical), TRBV10-2 (62% identical), TRBV10-3 (61% identical), TRBV10-1 (59% identical), TRBV27 (57% identical), TRBV24-1 (52% identical), TRBV25-1 (52% identical), and 39 more.